CD4 (CD4 molecule)
Diseases named in the same sentence as CD4 in open-access papers (continued):
Sharing a sentence is not in itself a finding about the gene and the disease.
Obesity (continued). "Therefore, both Foxo1 and Foxo3 in CD4+ T cells should be molecular targets for the prevention and treatment of obesity." (PMID 31756626, 2019). "γδ T cells thereby further activate CD4+ T helper cells in obesity." (PMID 31379820, 2019). "LsAg treatment reduced IFN-γ and IL-17+ CD4+ T cell frequencies during obesity." (PMID 31736971, 2019). "In addition, proportions of inflammatory CD4+ T cell subsets increase in obesity, whereas regulatory T cells (Treg cells) decrease." (PMID 29868016, 2018). "It was previously reported that obesity favors the recovery of CD4+ T-cell counts." (PMID 30505292, 2018). "Subsequently, T cells were found to be elevated in adipose tissue in obese mice and humans, and effector T cells, including CD4+ helper T (Th) cells and CD8+ cytotoxic T lymphocytes (CTLs), may serve as active players in obesity-associated WAT inflammation." (PMID 30459770, 2018). "However, the Treg cellular proportion of all AT CD4+ expressing T cells decreases during the development of obesity, yet controversy exists." (PMID 29186929, 2017). "In this way, we show how a modified version of the CD4+ T cell molecular network model proposed before, that now includes IL12, IL-27, and hyperinsulinemia, seems to mediate the observed cellular behavior in obesity-associated chronic inflammation." (PMID 28651594, 2017). "Metformin improves Treg/Th17 balance in CD4+ T cells in mice with high-fat diet-induced obesity." (PMID 27057099, 2016). "Adipose tissue macrophages from obese mice were more potent stimulators of proliferation of OVA-specific CD4+ T cells than adipose tissue macrophages from lean mice, thereby demonstrating that obesity-related inflammation promotes antigen-specific activation of T cells by APCs." (PMID 26146464, 2015). "In our study, to investigate whether diet-induced obesity can attract more CD4+IL-17+ T cells into adipose tissues, the CD4+T cells from HFD and ND adipose tissues were isolated by micro-beads and cultured them with PMA and ionomycin at 37°C for 4 hours." (PMID 24642966, 2014). "Although the skewed pro-inflammatory phenotype of CD4+ T subsets that include Th1, Th17, and Treg cells is frequently reported, there is no study at present on the frequencies and function status of Th22 cells in obesity and T2D patients." (PMID 24465695, 2014). "Because obesity could be associated with ART and better CD4 and viral responses, higher BMI will be the direct contributor to hypertension." (PMID 25490037, 2014). "Place of residence, household wealth, self-reported TB, high blood pressure diagnosis in the past year and obesity were not independently associated with CD4 cell counts in either HIV-infected and HIV-uninfected adults." (PMID 23894603, 2013). "In the group ≥40 years predictors of subclinical atherosclerosis were overweight and obesity (OR = 2.53, 95% CI, 0.85–7.54), current CD4 ≥350 cells/mL (OR: 2.81, 95% CI: 1.22–6.47) and NNRTI use ≥ 5 years (OR: 2.65, 95% CI: 1.10-6.37) or PI use >5 years (OR: 1.81, 95% CI: 0.38-8.59)." (PMID 23773229, 2013). "Interestingly, emerging studies have indicated that obesity selectively promotes the expansion of IL-17 producing CD4+ T (Th17) cells in adipose tissues, exacerbating autoimmunity in murine models." (PMID 24223854, 2013). "Recent studies reported that obesity could also result in a change in CD4+ T cell subsets, including pro-inflammatory Th1 and Th17 cells and anti-inflammatory regulatory T cells (Treg) in adipose or immune-associated tissues." (PMID 23531279, 2013). "In the ≥ 40 y group, male sex, overweight and obesity were also associated with subclinical atherosclerosis; however, factors related to HIV and HAART (CD4 above 350 cells/mL and use of NNRTI for at least 5 years) were also associated with subclinical atherosclerosis in this age group." (PMID 23773229, 2013). "Our data show that murine obesity lead to splenic CD4+ T cell activation." (PMID 21298111, 2011).
Obesity (continued). "CD4 count below 200 cells/mm3, obesity, and ART use did not increase the risk of significant fibrosis." (PMID 20465840, 2010). "Age ≥ 40 years (adjusted odd ratio (AOR) = 3.86; 95% CI: 1.08–13.73; and p=0.037), CD4 cell counts ≥ 500 cells/mm3 (AOR = 2.95; 95% CI: 1.01–8.59; and p=0.029), and insufficient physical activity (AOR = 4.6; 95% CI: 1.53–13.84; and p=0.007) were significantly associated with overweight and obesity." (PMID 39735593, 2024). "Conversely, these genes show a negative correlation with other immune cells, such as naive B cells, plasma cells, CD8 T cells, CD4 T cells, regulatory T cells, and activated NK cells, which might suggest a complex interplay between these genes and the immune response in obesity." (PMID 39594522, 2024). "Moreover, the placenta normally helps to skew the maternal and fetal environment toward a CD4+ helper T cell type-2 (Th2) and anti-inflammatory profile, whereas obesity and other stress factors create a more CD4 + helper T cell type-1 (Th1) and inflammatory gestational environment." (PMID 38494514, 2024). "Moreover, our research showed that BHLHE40 amplifies the inflammatory response in the pathogenesis of obesity by instigating the adaptive immune response of Treg cells and CD4+ T cells and promoting the chemotaxis of vital immune molecules, such as CCR, CXCL, and TNFRSF, in tissues." (PMID 39351493, 2024). "Moreover, participants with Class II obesity displayed an increase in the percentage of T17-like CD4+CD8+ Tf cells compared to nOB, while in the remaining groups, T17-like cells tended to be decreased (nOB: 15% ± 14.5; OBII: 20% ± 12.3; OBIII: 11% ± 9.5; OBIV: 6.9% ± 3.8; OBII vs. OBIV, p < 0.05)." (PMID 38397455, 2024). "Obesity-related inflammation is mediated by excessive adipose tissue storage and subsequent apoptotic-related macrophage infiltration, as well as neutrophil, CD4+ and CD8+ T cell recruitment that consequently leads to insulin resistance within the adipose tissue." (PMID 37372149, 2023). "Likewise, CD4 cells secreted cytokines mediate obesity and related metabolic complications." (PMID 36517853, 2022). "Therefore, this study aimed to clarify the impact of obesity on CD4+ T cells in the TIME." (PMID 36611881, 2022). "Furthermore, in the present study, HFD-induced obesity promoted the reduction in number and exhaustion of CD4+ T cells in the peripheral blood by tumor inoculation and similarly led to the reduction in number and exhaustion of CD8+ and CD4+ T cells in the tumor." (PMID 36611881, 2022). "Also, CD4+ Th1 cells are reported to be involved in obesity-related insulin resistance." (PMID 35235789, 2022). "Furthermore, the full biological impact of obesity on the CD4+ and CD8+ T cell responses necessary to drive ICB efficacy remains unknown." (PMID 34064933, 2021). "Interestingly, CD4+ T cells were identified to exhibit long-lasting obesity memory and induction of body mass regain in a weight gain–loss–regain C57BL/6J model, suggesting the potential role of an immune cell stimulated inflammatory condition in promoting obesity relapse." (PMID 32471061, 2020). "However, obesity suppresses the recruitment of these lymphocytes to abdominal fat and down-regulates tolerogenic CD4+ T-regulatory cells, which could also lead to meta-inflammation." (PMID 31404145, 2019). "However, in contrast to Winer and colleagues, we also found increases in IFN-γ+ CD4+ T cells in spleen and IL-17+ CD4+ T cells in adipose tissue during obesity, which may be due to the prolonged HFD treatment in our study, diet composition, and gut microbiota." (PMID 31736971, 2019). "In addition to uncertainties over specific cell types that provide the MHC Class II molecules needed for CD4+ T cell activation, numerous costimulatory molecules on the APC that strengthen, sustain or ameliorate TCR activation have also been implicated in obesity-associated T cell inflammation." (PMID 31379820, 2019).
Obesity (continued). "Collectively, these data reveal a novel role of adiponectin in controlling pro-inflammatory CD4+ T cells during obesity and suggest that the beneficial role of helminth infections and helminth-derived products on obesity and insulin resistance may be in part mediated by adiponectin." (PMID 31736971, 2019). "CD4+ and CD8+ T cells populate the human adipose tissue and the Th1:Th2 balance is highly associated with systemic inflammation and insulin resistance; in addition, MHCII and costimulators CD86 and CD40 play essential roles in obesity-induced adipose tissue inflammation." (PMID 29765984, 2018). "Although much progress has been made on our understanding of the role of AT-resident CD4+ T cells in regulating metabolism, it is still unclear which cells are the major APCs at different stages of obesity and whether these APCs cooperate to activate CD4+ T cells." (PMID 30233575, 2018). "Therefore, the observation of a decreased circulating number of a protective subset of lymphocytes, as well as of an increase in CD4+ effector memory cells might open clinical and therapeutic perspectives also in obesity." (PMID 29758052, 2018). "However, how AT-resident CD4+ T cells are activated during obesity remains controversial." (PMID 30233575, 2018). "CD4+ Th1 cells may have similar contributions to obesity-related insulin resistance; reductions in adipose tissue Th1 by ablation of major histocompatibility complex (MHC) class II molecule (MHCII) on adipocytes or ATMs were associated with improved insulin resistance in obese mice." (PMID 30619305, 2018). "In addition, these experiments suggest that CD4+ cells are necessary for HFD-induced obesity." (PMID 26796537, 2016). "Notably, at least two of the CD4+ subpopulations, i.e. Th1 and Th17 cells, are pro-inflammatory and their numbers are significantly elevated in AT of metabolically unhealthy obese subjects or in diet-induced obesity in mice." (PMID 25894202, 2015). "However, regression analyses using absolute TREC numbers in 1 ml peripheral blood (not those in CD4 or CD8 T cells) still found inverse associations with most obesity indicators." (PMID 24651652, 2014). "Interestingly, adoptive transfer of CD4+ cells especially Th2 CD4+ T cells, which produce IL-4 and IL-13, rescues HFD-induced obesity and insulin resistance in Rag1 deficient mice suggesting that Th2 cytokines such as IL-4 and IL-13 suppress HFD-induced inflammation to improve insulin sensitivity." (PMID 23781214, 2013). "Thus, CD4+ cells are key in the control of disease progression in diet-induced obesity." (PMID 24106481, 2013). "The determination of iNKT cells absolute counts clarified the origin of this disturbance: while the number of CD4+ iNKT cells remains unaffected, the count of CD4−CD8− iNKT cells is significantly decreased in obesity." (PMID 41000378, 2025). "From an immune cell perspective, independent associations within the tumor compartment were observed for iCCA (myosteatosis: TIM-3+CD8+cells; obesity: PD-1+TIM-3+CD4+cells) and for pCCA (myosteatosis: PD-L2+CD68-cells and CD4+cells)." (PMID 39760117, 2024). "CD4+ (Th) and CD8+ (Tc) T lymphocytes have been described as displaying an altered phenotype and function in obesity and metabolic dysfunction." (PMID 38397455, 2024). "In obesity, CD8+ effector memory T cells, CD4+ Th1 cells, and B2 cells are increased in AT and promote AT inflammation, while regulatory T cells and Th2 cells, which usually function as immune regulatory or type 2 inflammatory cells, are reduced in AT." (PMID 38455510, 2024). "B-cells are partly responsible for the generation of CD153 + PD-1hi CD4 T-cells in VAT, which in turn contribute to inflammation and metabolic disorders in obesity." (PMID 38317257, 2024). "Obesity increases CD8+ effector memory T cells, CD4+ Th1 cells, and B2 cells, but reduces Treg and Th2 cells, in AT." (PMID 38455510, 2024).
Obesity (continued). "The OB participants had a lower percentage of TIM-3+ T1-like CD4+CD8+ T cells, especially in Class III obesity, IS, and IRn, compared to nOB (p < 0.05)." (PMID 38397455, 2024). "Another inflammatory factor related to obesity-induced ASM remodeling is the involvement of adaptive immune cells, particularly CD4+ T cells." (PMID 38562155, 2024). "A decreased percentage of PD-1+ T1-like CD4+CD8+ T cells in OB (57% ± 24.9 vs. nOB: 68% ± 26.2, p > 0.05) was also observed, especially in Class III obesity (50% ± 24.3)." (PMID 38397455, 2024). "The development of obesity-induced ASM remodeling is an intricate process influenced by factors like neutrophils, neutrophil elastase, CD4+ T cells, HMGB1 protein, TGF-β1, leukotrienes, and their derivatives." (PMID 38562155, 2024). "There was an increase of CD3+ T lymphocytes (mainly CD4+, CD4+CD62-, and CD8+CD45RO+ T lymphocytes) and an increase in the TBF percentage (severity of obesity)." (PMID 37334132, 2023). "To further investigate the relationship of obesity with the immunophenotype of T cells in participants with T2D, we analyzed the CD28 − CD57+ senescent subset of the CD4+ and CD8 + T cells using flow cytometry." (PMID 37735474, 2023). "The percentages of CD4+, CD4+CD62-, and CD8+CD45RO+ T lymphocytes increased as the degree of obesity increased." (PMID 37334132, 2023). "During the progression of obesity, lipids released from adipocytes are also involved in the enrichment of IFN-γ–producing CD4 T cells in VAT." (PMID 36685567, 2022). "Our model revealed that the acceleration of tumor growth due to obesity is not only CD8+ T cell-dependent, as previously reported, but is also CD4+ T cell-dependent." (PMID 36611881, 2022). "In particular, many studies have shown that CD4 T cells are deeply involved in the homeostasis of VAT endocrine and metabolic functions and in obesity-related chronic inflammation." (PMID 36685567, 2022). "This review discusses the marked transformation of CD4 T cells in VAT and systemic organs as a consequence of obesity-related microenvironmental changes." (PMID 36685567, 2022). "Aerobic training appears to improve cluster of differentiation 4 (CD4) function in human immunodeficiency virus (HIV) patients, while chronic exercise diminishes the harmful effects of obesity, aging, and chronic infections on T cells." (PMID 35632525, 2022). "Although one report suggests a positive correlation between CD4+ central memory cells and BMI in aged patients, it would be interesting to know whether memory B and T cells are effectively generated following the infection and, especially, after vaccination in patients with obesity." (PMID 35837843, 2022). "In metabolic diseases, such as obesity, NAFLD andT2D, CD4+ T cell differentiated cells, such as Th1, Th2, Th17, and Tregs, all play potential roles in disease regulation or progression." (PMID 36428983, 2022). "Many studies have shown that CD4+T cells exist in adipose tissue, NAFLD, and atherosclerotic plaques in obesity." (PMID 35784695, 2022). "Premature immunesenescence, accelerated aging of the immune system, particularly of the CD4+ and CD8+ T cell compartments, has been found in people with obesity or type 2 diabetes." (PMID 35646955, 2022). "As previously reported, obesity led to a decreased frequency in CD3+ and regulatory T cells and an increase in the percentage of CD4+ T cells." (PMID 35472214, 2022). "However, the impact of obesity on CD4+ T cells remains unclear." (PMID 36611881, 2022). "High fitness levels—usually displayed by chronic exercisers—associated with increased Tregs in CD4+, CD25high, and CD127low and memory of Tregs in CD4+, CD25+, and CD39+, even in obesity." (PMID 35632525, 2022). "CD4 + T cells produce interferon- γ (IFN- γ) which contributes to inflammation, glucose intolerance, and insulin resistance in diet-induced obesity mice." (PMID 35858901, 2022).
Obesity (continued). "The changes in CD4/CD8 ratio also depend on BMI (normal, overweight and obesity) in both active and inactive older adults." (PMID 33752623, 2021). "The current study investigated the impact of the surgical intervention by the LGS on CD4+ T regulatory cells and CD4+ T-lymphocytes subpopulations, which are: naïve, TCM, and TEM cells in the peripheral blood of class 111 obesity subjects after 12 weeks." (PMID 33981153, 2021). "Obesity has also been found to increase the expression of major histocompatibility complex (MHC) class II molecules on adipocytes and to activate adipose CD4+ T lymphocyte-related inflammation." (PMID 34557550, 2021). "In contrast to this, we found an increase in the CD4/CD8 ratio in the morbid obese patients, which confirms earlier studies in obesity." (PMID 34354700, 2021). "The results of GSEA based on immunity and immunology showed that the level and status of immune cells such as macrophages, CD4 + T cells, CD8 + T cells, and B cells have changed during the progress of obesity, which also involves cytokines such as IL-4." (PMID 34712134, 2021). "Regarding the obesity-induced AT inflammation, both M11cKO mice and MMKO mice showed decreased CD4+ T cells." (PMID 34445379, 2021). "This suggests that antigens (probably self-peptides) presented by MHC class II induce the expansion of CD4+ T cells in VAT and their differentiation into inflammatory effectors during the development of HFD-induced obesity." (PMID 34572084, 2021). "To test if maternal obesity reprograms resting cord blood CD4+ T cells, we performed droplet-based single cell RNA sequencing (scRNA-Seq) of UCBMC from babies born to lean mothers (n=2) and mothers with obesity (n=2)." (PMID 33912153, 2021). "In the present study, the obesity-induced gut dysbiosis increased the immunopathology, IFN-γ levels and frequency of CD4+IFN-γ+IL-17− cells." (PMID 34359902, 2021). "The majority of publications detailing the impact of obesity on T cells have focused on the CD8+ subset, but here we are reporting an obesity-induced reduction in both CD4+ and CD8+ T cell effector responses." (PMID 34064933, 2021). "Within the aged VAT, similar to obesity, there is an expansion of various T cell populations including CD8+ T cells and CD4+ T cells." (PMID 32499756, 2020). "In obesity and insulin resistance visceral adipose tissue shows a higher CD8+:CD4+ T-cell ratio and macrophage M1 polarization, that represent a chronic pro-inflammatory response that, via cytokines activation, contributes to HFpEF progression." (PMID 32477267, 2020). "In general, the expression of TIM3 on CD3+, CD4+, and CD8+ T cells in patients with obesity was increased, while they went down significantly in patients with obesity and T2DM." (PMID 33123595, 2020). "The adipocytokines leptin and IL-6 inhibit regulatory T cells, whereas obesity alters cell-mediated Th1 immune responses, resulting in CD3 and CD4 T helper cells and CD8 T suppressor/cytotoxic cells defects." (PMID 32256575, 2020). "Compared to CD4+ T cells, the role of CD8+ T cells during obesity is less explored despite the fact that CD8+ T cells produce more IFN-γ than CD4+ T cells." (PMID 31736971, 2019). "Our study underscores an active involvement of CD4+ and CD8+ Th1 and Th17 cells in obesity, which along with coordinated participation from macrophages and B cells propagates a robust pro-inflammatory milieu." (PMID 31736971, 2019). "Depleting macrophages and B cells at obesity onset was sufficient to mitigate CD8+ T cell inflammation, while CD4+ T cell inflammation was rather subject to regulation by the adipocyte secreted insulin sensitizer adiponectin." (PMID 31736971, 2019). "In contrast to conventional CD4+, CD8+ T cells, and γδT cells, Treg are dramatically decreased in adipose tissue in obesity, and expansion of Treg in obese mice protects against adipose tissue inflammation, with decreased ATMs and related inflammatory markers." (PMID 30619305, 2018).